RN7SL734P (RNA, 7SL, cytoplasmic 734, pseudogene)
Gene: Miscellaneous RNA gene on chromosome 12 (75,957,833 to 75,958,130, reverse strand). Ensembl gene ENSG00000243420.
Homologues: Orthologues: chimpanzee Metazoa_SRP (99% identical), macaque Metazoa_SRP (86% identical). Paralogues in human: RN7SL1 (80% identical), RN7SL2 (80% identical), RN7SL3 (80% identical), RN7SL597P (79% identical), RN7SL126P (79% identical), RN7SL586P (78% identical), RN7SL357P (78% identical), RN7SL650P (78% identical), RN7SL147P (78% identical), RN7SL448P (78% identical), RN7SL551P (78% identical), RN7SL709P (78% identical), and 703 more.